STAT1 (signal transducer and activator of transcription 1)
Diseases named in the same sentence as STAT1 in open-access papers (continued):
Sharing a sentence is not in itself a finding about the gene and the disease.
infection (continued). "In addition increased levels of Ip10, Irf1, Stat1, Icsbp, at day 1 post infection in the blood of Ifnar1-/- as compared to the WT mice is in keeping with type I IFN inhibition of Th1 responses and could explain the subsequent reduction in bacterial load in the Ifnar1-/- infected mice." (PMID 26918359, 2016). "E. chaffeensis blocks tyrosine phosphorylation of Stat1, Jak1, and Jak2 in response to IFN-γ through raising PKA activity in THP-1 cells soon after infection." (PMID 27303657, 2016). "However at day 3 post infection diminished expression of Stat1 was observed across all three tissues, following infection in the Ifnar1-/- compared to the WT mice, which may be explained by a dependence on type I IFN signaling or may result from the lower bacterial load in the Ifnar1-/-." (PMID 26918359, 2016). "In contrast, accumulation of phospho-STAT1 was reduced by infection with NDV, which affected the level of total STAT1." (PMID 26859759, 2016). "Thus, Jak/Stat-1 pathway activation occurs only when an active infection is established in the host, and it is plausible that the differences in the expression levels of p-tyr701Stat-1 could be due to different bacterial survival mechanisms or differences in their life cycles within macrophages." (PMID 27437406, 2016). "Localised productive infection triggered a broad innate response, with type-1 interferon sensitive IRF-7, STAT-1, TRIM5α and ApoBEC3G genes all upregulated during the acute phase but induction did not prevent viral persistence." (PMID 25162725, 2014). "The capacity of PMLIV to inhibit VSV protein synthesis was still maintained in cells depleted for STAT1, further demonstrating the intrinsic anti-VSV effect of PMLIV at 12 h post-infection." (PMID 24586174, 2014). "The importance of balanced cellular STAT levels has been shown for infection with Lymphocytic Choriomenengitis Virus (LCMV): the ratios of basal and induced STAT1/STAT4 determine the innate and adaptive immune cell activities." (PMID 24489749, 2014). "Some of them showed an amplification of the differential regulation during the time-course of WNV-infection (early vs. mock and late vs. early), such as PPID and PCM1 (down-regulated) and TAPBP and STAT1 (up-regulated)." (PMID 23874584, 2013). "The replication of encephalomyocarditis virus (EMCV, a positive ssRNA virus) was also inhibited, five-fold by high levels of wild-type STAT1/STAT2/IRF9 or four-fold by Y701F-STAT1/STAT2/IRF9, when assayed 6 h after infection." (PMID 24065129, 2013). "Others have demonstrated an age-related decrease in IFN response through STAT1, IRF1 and IRF7 signaling following infection with West Nile Virus." (PMID 23936572, 2013). "Taken together, these data demonstrate that Toxoplasma pre-infection of BMDC leads to synergistic activation and binding of atypical STAT1 complexes to GAS sequences in response to IFNγ." (PMID 23527309, 2013). "In contrast, infection with WT or F170S HPIV1 was very efficient and resulted in a decrease in Stat1 phosphorylation that was evident in the total lysate." (PMID 22355301, 2012). "The upregulation of ISGs (i.e. CXCL9, IRGM1, PSMB9, STAT1 and UBD) in DBA/2 compared to C57BL/6 mice was confirmed by RT-qPCR at all days post-infection." (PMID 23006927, 2012). "In cells transfected with control siRNA, Candid#1 JUNV infection led to induction of ISG15 protein expression and STAT1 phosphorylation as expected." (PMID 22629479, 2012). "The infection of IGR-39 cells with delNS1 or delNS1-IL-15, however, resulted in STAT1 and STAT2 phosphorylation and upregulation of MxA expression indicating a cellular interferon response." (PMID 22563505, 2012). "The infection with pH1N1 resulted in considerable decrease in the expression of cytokine and other immune genes namely IL8, STAT1, B2 M and IL4 compared to seasonal H1N1." (PMID 21439068, 2011).
infection (continued). "Cytokines like CCL5, small inducible cytokine A2, IL8 and other immune responsive genes like STAT1, IRF1 and B2 M were found to be up-regulated at this time point post infection with seasonal influenza virus." (PMID 21439068, 2011). "Stat1−/− mice have been utilized in a large number of studies to delineate the roles of Stat1 and IFN in controlling infection and mediating IFN-dependent gene expression." (PMID 21915277, 2011). "Both STAT1−/− and STAT2−/− mice possessed similar levels of TNF in the serum at 72 hours post-infection, which were 4–5 fold higher than that detected in wild type mice." (PMID 21379341, 2011). "This suggests that early control of DENV replication requires the combined function of STAT1 and STAT2, but STAT2-independent mechanism(s) begin to restrict replication by 24 hours post-infection." (PMID 21379341, 2011). "STAT-1 knockout mice also had decreased MCH, MCHC, and hemoglobin levels during infection, which can be indicative of the observed decreased hematocrit levels." (PMID 21672221, 2011). "Consistent levels of STAT1 phosphorylation were detected at all time points in wild type cells, whereas levels of phosphorylated STAT2 were highest at 12 hours after infection and decreased over time." (PMID 21379341, 2011). "We observed the mRNA level of EGFR to be up-regulated, and downstream signaling protein, such as STAT3, STAT1, AKT3 and MKK4 also showed up-regulation at 4 days post infection." (PMID 21172007, 2010). "Cells were sorted and infected with Ad5/3-Delta24 and four and 24 hours following infection, mRNA was collected and analyzed for type I interferons (IFNα and IFNβ) interferon regulatory factors IRF3, IRF7 and transcription factor STAT1 expression." (PMID 21079774, 2010). "We infected STAT1-/- and STAT+/+ DCs with 10 PFU/cell of HSV-1 McKrae and then harvested cells at 0, 4, 12, 24, and 48 hr post-infection." (PMID 19439086, 2009). "Genes that were induced during the first 2 days after infection included early stress response genes (early growth response, Fos, Jun) and IFN responsive genes (MX1 and 2, STAT-1, IFN-γ inducible protein-10, guanylate binding protein-1 and -2)." (PMID 17725815, 2007). "Similar to our in vitro data, infection with B.anthracis was only a weak inducer of IFN signaling, as manifest by minimal BALF STAT1 phosphorylation." (PMID 17710136, 2007). "Here, we demonstrate that H1N1-infected pulmonary microvascular ECs (PMVECs) during later stage of infection function as antigen-presenting cells that activate resident CD8+ T cells via MHC-1 and co-stimulatory CD40, promoting viral clearance through IFNγ-STAT1-dependent positive feedback loop." (PMID 41542053, 2026). "Mice lacking signal transducer and activator of transcription 1 (STAT1-/-) have been shown to succumb to infection by related arenaviruses, including Machupo virus, and were investigated for their susceptibility to CHAPV infection." (PMID 41902296, 2026). "In addition, perturbation of Hrf-063 or eIF4A1 altered the expression of STAT1 and CAV1, and Hrf-063 regulated ISG15 and STING1 transcription in a time- and infection-dependent manner." (PMID 42306525, 2026). "Additionally, MGF505-4R was able to coprecipitate with STAT1 and STAT2 during infection with ASFV-WT." (PMID 40618140, 2025). "However, the levels of other innate immune signaling proteins, such as JAK1, STAT1, p-STAT1, IRF3, or IRF1, remained similar after infection with UL88-STOP or WT TB40/E." (PMID 40638072, 2025). "STAT-1 knockout mice, which are not responsive to type I or type II IFN signaling, are susceptible to LASV and develop hearing loss following infection with non-pathogenic LASV isolates." (PMID 40022100, 2025). "Following inoculation, both Stat1 and Rag1 KO mice showed no clinical signs of infection or mortality." (PMID 40304490, 2025). "Therefore, we transfected RAW264.7 cells with STAT1 and STAT2 specific siRNAs, followed by infection with RSV." (PMID 40245000, 2025).
infection (continued). "Moreover, STAT1-dependent chemokines including CCL5, CCL8, CXCL10, and CXCL11 showed a slight increase during the early stage of infection, the most significant increase occurred after 10 h.p.i, peaking at 24 h.p.i." (PMID 40934228, 2025). "Infection by C. parvum and inhibition of STAT1 did not influence the number of HCT-8 cells, but did increase the number of C. parvum." (PMID 40681213, 2025). "The PRV UL41 protein, as well as the mRNAs of JAK1, Tyk2, STAT1, STAT2, and IRF9, were detectable in the RIP mixture, signifying that the mRNAs of JAK1, Tyk2, STAT1, STAT2, and IRF9 are among the targets of PRV UL41 during infection." (PMID 41341288, 2025). "Yet, the transcription factors that drive TH1 differentiation (T-bet and STAT1) were no longer induced, and neither were the costimulatory molecules or inhibitory receptors observed in first infection." (PMID 40214640, 2025). "The results showed that infection did not induce PKR expression by inhibiting the phosphorylation of STAT1 and subsequent binding in the PKR promoter." (PMID 40521699, 2025). "STAT1-deficient mice are highly sensitive to MNV and succumb to infection, unlike immunocompetent animals." (PMID 40464581, 2025). "In addition, at later stages of infection, recognizing structural DENV-PAMPs and/or viral replication intermediates induces both NF-kB- and STAT1-dependent pro-inflammatory responses, leading to a cytokine storm." (PMID 40934228, 2025). "In contrast, ruxolitinib had a dramatic suppressing effect on STAT1, P-STAT1, and MX1 upregulation when it was added also pre-infection, also resulting in a dramatic increase in VSV protein accumulation, ultimately partially reversing the phenotype of siMETTL3-transfected SUIT-2." (PMID 40214229, 2025). "Stat1 is important for the signaling cascade for IFN-λ, so these results would not be consistent with the hypothesis that IFN-λ is restricting VA1 infection of the GI tract." (PMID 40304490, 2025). "Concomitantly, genes involved in inflammatory and interferon-related responses, including IFN-γ, IL-12b, STAT1, STAT3, IL-6, TNF-α, CXCL9, CXCL10, and CXCL5, were significantly upregulated, indicating a strong pro-inflammatory environment during peak infection." (PMID 40630939, 2025). "As expected, increased levels of phosphorylation of IRF3 and STAT1 were found in AGO2 knockout cells after infection with DelNS1 WSN virus, regardless of the presence of DROSHA." (PMID 40949099, 2025). "While the acute stage of MHV68 infection was not affected, we found opposite, anatomic site-dependent effects of B cell-intrinsic STAT1 expression during chronic infection." (PMID 39440973, 2024). "Seven differentially expressed genes (DDX58, STAT1, MX1, IRAK1, MAPK11, RELA, and ICAM1) were randomly selected and quantified using qRT-PCR to validate the differential expression observed in A549 cells using RNA-Seq across varying infection time points." (PMID 38673764, 2024). "Unlike the decrease in persistent MHV68 lung replication observed in mice lacking STAT1 in B cells, infectious MHV68 levels in the lungs were not altered by the B cell-specific IFNAR1 deficiency at 16 days post-infection." (PMID 39440973, 2024). "Furthermore, in the post-infection assays with rotavirus and C. sorokiniana, we observed a significant (p < 0.05) relative expression of SOCS3, STAT1, and STAT2." (PMID 38791551, 2024). "Notably, LNCaP cells exhibit downregulated JAK1 and STAT1 compared to PANC-1 cells, potentially influencing their differential responses upon infection." (PMID 38425844, 2024). "We retrieved lists of the known targets of NF-kB/p65, STAT1, STAT2, IRF2, and IRF3 and extracted from these lists genes that were differentially expressed either during infection in Dicer WT or Dicer N1 cells, or between mock-infected Dicer WT and Dicer N1 cells." (PMID 38287188, 2024).
infection (continued). "A combination of B. longum and C. sorokiniana was used to study its effect on the antiviral response in HT-29 by measuring the mRNA levels of IFN-γ, IL-10, SOCS3, STAT1, and STAT2 genes in cells with the combination of B. longum/C. sorokiniana in the pre- and post-infection assays with rotavirus." (PMID 38791551, 2024). "Taken together, the data indicate that, in the absence of SOCS3, infection leads to a stronger activation of STAT1, resulting in the enhanced expression of ISGs and reduced virus propagation." (PMID 39201692, 2024). "To explore this relationship among participants in the replicative infection group, we compared MX1 and IFI27 levels with the average expression of a multigene signature (“STAT1 regulated module”) that we had previously derived and validated as a measure of type 1 IFN bioactivity." (PMID 39616162, 2024). "Moreover, in the post-infection assays (cells infected and further treated), the mRNA levels of SOCS3, IL-10, and IFN-γ were significantly (p < 0.05) upregulated, whereas STAT1 was downregulated." (PMID 38791551, 2024). "Using cervical epithelial HEp2 cells that were validated to respond homogeneously to physiologically relevant levels of IFNγ, we observed reduced expression and activation of both STAT1 and its kinase JAK2 at early stages of infection, with concomitant reduction in expression of ISGs." (PMID 39194253, 2024). "Similarly, phospho-STAT1 and phospho-STAT2 levels were increased in UL26ΔC-infected cells relative to mock or WT infection." (PMID 38768227, 2024). "PHEV significantly upregulated ISG15 expression (>1.5 log2FC) at all three time points, and it appears ISG15 does interact with HERC5, IFIT1, PKR, TRIM25, STAT1, and USP18, as their expression was also enhanced (>1.0 log2FC) at various timepoints during ALI-PRECs infection." (PMID 38932231, 2024). "In the biological role of IFN-γ signaling against infection with intracellular pathogens, IFN-γ could activate the transcription of genes of proinflammatory cytokines or chemokines after STAT1 phosphorylation." (PMID 38792802, 2024). "Thus, we detected the activation of STAT1 and STAT4 at 8, 12, and 24 hours post-infection as possible downstream signaling of the induced pyroptosis." (PMID 39119293, 2024). "In contrast to no STAT1 activation in CVB3-infected WT cells, the infection of SOCS3 knockdown cells resulted in strongly elevated p-STAT1." (PMID 39201692, 2024). "Furthermore, infection of IFNAR−/− mice with CCHFV also led to the development of coagulopathy and severe organ damage, similar to the observed effects in the STAT1−/−model." (PMID 37753088, 2023). "Therefore, it is possible that the enhanced pSTAT1 detected in WT infection is indirectly due to UL138 regulation of type 1 interferon secretion and activation of STAT1 in neighboring uninfected cells." (PMID 37289831, 2023). "CAV21 infection of mock-treated cells led to blunted p-STAT1(Y701) without downstream IRF7 induction or type-I IFN release." (PMID 37962360, 2023). "Expression of Stat1 was not detectable after infection, as expected after inhibition of type I IFN signaling." (PMID 37289084, 2023). "Pretreatment with IFN-α2B for 16 hours before HSV-1 infection significantly decreased viral replication levels relative to untreated cells 72 hours after infection in healthy control cells, but not in STAT2-, IFNAR1-, STAT1-, and IRF9-deficient cells." (PMID 36976641, 2023). "After the infection by the SARS-CoV-2 proteins, NSP1, and ORF6, STAT1." (PMID 37924089, 2023). "Subsequently, studies found that the in vivo and in vitro infection of CSFV could induce the expression of IFN-III and several key ISGs through the activation of signal transducer and activator of transcription 1 (STAT1) and NF-κB." (PMID 36936761, 2023).
infection (continued). "Here, we reported that IL-22 expression was highly facilitated after DHAV-1 infection both in vitro and in vivo, and the increase in expression might be due to duck STAT3 directly antagonizing STAT1 and leading to an increase in IL-22 promoter activities." (PMID 37391858, 2023). "Critically, targets of transcription factors known to regulate inflammation (IRF1, STAT1, STAT3) and fibrosis (SMAD2/3, EGR1, TEAD4, YAP1) appeared to be highly induced in the host, consistent with prior reports of infection-dependent induction of pro-inflammatory and pro-fibrotic gene expression." (PMID 36923592, 2023). "Seven hours post infection, IFNβ produced by the first responders will diffuse to neighboring, yet nonresponding cells, thereby activating their IFNARs, followed by the subsequent translocation of ISGF3, consisting of STAT1, STAT2, and IRF9." (PMID 36629318, 2023). "Lacking STAT1, infection triggers a marked immune response discoordination with hypercytokinemia, significantly more inflammation, and increased bacterial loads, as has been observed with bacterial, protozoan, and viral infections." (PMID 37228668, 2023). "Between the two viruses, neither the expression nor the phosphorylation level of STAT1 was changed at 4 h after infection." (PMID 37296165, 2023). "tularensis LVS-infection; a significant upregulation of genes involved in RAS pathway including Ccl2, Nfkb, p38 Mapk, Ras, Stat1, Stat3 and Tnf-α; and an upregulated expression of IFN-γ pathway genes such as Bak, Bax, Ifit, Ifn-γ, Irf, Isg, Oas1, Psmb8, Ptpn2, Stat and Tap1." (PMID 37266014, 2023). "Furthermore, STAT-1-mediated signaling induces the production of IFN-y in macrophages, and when negatively regulated, it favors infection." (PMID 37376405, 2023). "In WT infection at 48 hpi, we detected pSTAT1 bound at both site 1 and 2 upstream of UL138 relative to the uninfected IRF1 control, whereas we did not detect binding of STAT1 to these sites in ΔUL138STOP infection." (PMID 37289831, 2023). "Human immunodeficiency virus (HIV) and the closely related simian immunodeficiency virus (SIV) both induce STAT1 phosphorylation, where it plays a role in maintaining the infection, and in the case of HIV, it was independent of IFNγ." (PMID 37655893, 2023). "TP63, FOXA1, STAT1, ELK1, FOS, and JUN are TFs in various lung injury or infection types." (PMID 36911695, 2023). "For example, a recent study showed that upon IFN-α treatment, although SARS-CoV-2 infection reduces STAT1 phosphorylation, the STAT1 activation was sufficient to induce ISGs to the similar level of cells without infection." (PMID 37377442, 2023). "We found that while the reduction in infection when p38β is depleted is significant, it is not appreciably rescued by STAT1-knockout, indicating that the mechanism of action of p38β is primarily STAT1-independent." (PMID 37345956, 2023). "Collectively, these data suggest that ORF6 is not sufficient to antagonize IFN signaling during infection but can attenuate STAT1 translocation upon exogenous stimulation with IFN-β with little impact on ISG expression." (PMID 37377442, 2023). "IFNɛ activated STAT1/2 pathways similar to IFNα and λ that were inhibited by ZIKV-encoded non-structural (NS) proteins, but not if IFNε exposure preceded infection." (PMID 36897927, 2023). "Phosphorylation of STAT1 was not detectable in uninfected cells but was observed as early as 12 hours post infection." (PMID 35584177, 2022). "In addition, downregulated phosphorylation of STAT1 and STAT2 were observed in ISG15-/- mice after infection with PRV in vivo." (PMID 36146669, 2022). "However, 1,25(OH)2D3 treatment not only inhibited p-STAT1 and p-STAT3 levels at 1 h post-infection, but also at 24 h post-infection in IPEC-J2 cells." (PMID 36142545, 2022). "In contrast, total STAT1 levels did not decrease following infection and stimulation, suggesting that SFNV and SFSV affect STAT1 phosphorylation and not STAT1 stability." (PMID 35720342, 2022).